OR10S1 (olfactory receptor family 10 subfamily S member 1)
Description:
Odorant receptor.
Synonyms: OR11-279
Gene: Protein-coding gene on chromosome 11 (123,976,661 to 123,977,781, reverse strand). Ensembl gene ENSG00000196248.
Subcellular location: Cell membrane
Pathways (Reactome):
Sensory Perception: Expression and translocation of olfactory receptors; Olfactory Signaling Pathway
Genetic constraint (gnomAD): Missense variants: 415 observed, 428.33 expected, observed/expected ratio (o/e) 0.97, 90% interval 0.89 to 1.05. Synonymous variants: 167 observed, 173.12 expected, observed/expected ratio (o/e) 0.96, 90% interval 0.85 to 1.1.
Homologues: Orthologues: mouse Or10s1 (85% identical), dog OR10S1 (84% identical), rat Or10s1 (82% identical). Paralogues in human: OR10G2 (52% identical), OR10G6 (52% identical), OR10G3 (51% identical), OR10G4 (50% identical), OR10G7 (50% identical), OR10G9 (49% identical), OR10G8 (48% identical), OR10D3 (45% identical), OR2K2 (43% identical), OR10A4 (42% identical), OR2S2 (42% identical), OR5V1 (42% identical), and 80 more.
Diseases named in the same sentence as OR10S1 in open-access papers:
OR10S1 is named in the same sentence as 1 disease in open-access papers, as found by Europe PMC text mining. Sharing a sentence is not in itself a finding about the gene and the disease.
OR10S1 shares sentences with these, for which no sentence is quoted: Epileptic encephalopathy (1 paper).